MYH11 (myosin heavy chain 11)
Diseases named in the same sentence as MYH11 in open-access papers (continued):
Sharing a sentence is not in itself a finding about the gene and the disease.
thoracic aortic aneurysm (36 papers, 2007 to 2026). An aneurysm formed in the wall of the proximal portion of the descending aorta proceeding from the arch of the aorta. "While gain-of-function variants in MYH11 are associated with thoracic aortic aneurysms and dissections, loss-of-function variants are linked to autosomal recessive Megacystis-Microcolon-Intestinal Hypoperistalsis Syndrome (MMIHS)." (PMID 42063440, 2026). "MYH11 mutation can lead to abnormal aortic development, and some scholars abroad consider it as a predictive factor for thoracic aortic aneurysm and bicuspid aortic valve occurrence." (PMID 40224383, 2025). "For example, our identification of rare MYH11 mutations in non-syndromic thoracic aortic aneurysms aligns with recent reports." (PMID 40110250, 2025). "Mutation of MYH11 causes familial thoracic aortic aneurysms and dissections with an increased prevalence of BAV." (PMID 37961530, 2023). "Rare pathogenic variants in the MYH11 gene are responsible for thoracic aortic aneurysms and dissections." (PMID 40225146, 2023). "Mutations in target genes of myocardin, including Myh11, Acta2, and Mylk, are known causes of thoracic aortic aneurysms with dissection (TAAD), but most studies show a limited genetic overlap between AAAs and TAAs." (PMID 37561588, 2023). "Further, increased AngII-mediated and insulin-like growth factor 1–mediated signaling, independent of TGF-β signaling, is thought to drive a form of inherited nonsyndromic thoracic aortic aneurysms associated with missense mutations in the MYH11 gene." (PMID 36472907, 2023). "Patient 1 had a large duplication covering nine genes including MYH11, a gene associated with familial thoracic aortic aneurysms and dissections." (PMID 35743335, 2022). "In previous studies, mutations in MYH11 have been identified in familial congenital heart disease and thoracic aortic aneurysms and dissections." (PMID 35845066, 2022). "Mutations in NOTCH1 are known to cause familial BAV disease, whereas mutations in MYH11 cause hereditary thoracic aortic aneurysms." (PMID 35711915, 2022). "Mutations in MYH11 cause a marked aortic stiffness, which is associated with thoracic aortic aneurysm/aortic dissection." (PMID 33083483, 2020). "Overexpression of MYH11 was able to increase ER stress and autophagy, and mutations in MYH11 caused syndrome-associated thoracic aortic aneurysm/ADs2,24." (PMID 29416002, 2018). "Mutations in MYH11 cause thoracic aortic aneurysm/dissection, and recurrent 16p13.1 duplications confer a risk for aortic dissection." (PMID 24826987, 2014). "However, vascular smooth muscle disease has also been attributed to mutations in actin and myosin genes with the discovery of mutations in ACTA2 and MYH11 in thoracic aortic aneurysms and dissections." (PMID 24676022, 2014). "Interestingly, missense mutations in the MYH11 gene are associated with thoracic aortic aneurysms." (PMID 36472907, 2023). "Familial thoracic aortic aneurysms and dissections (FTAAD), linked to mutations in genes like ACTA2 and MYH11, highlight the genetic heterogeneity of aortopathies." (PMID 40110250, 2025). "Common variants of the MYH11 gene are associated with CAD and high blood pressure, and SNPs in the FBN1 gene correlate with thoracic aortic aneurysm, coronary artery dissection, and blood pressure, according to the GWAS Catalog." (PMID 39125885, 2024). "One patient carried a CNV disrupting the COL3A1 and COL5A2 genes (vascular or hypermobility type of Ehlers–Danlos syndrome), and another patient a CNV in MYH11 (familial thoracic aortic aneurysms and dissections)." (PMID 35743335, 2022). "Whereas homozygous or compound heterozygous loss-of-function variants in MYH11 cause MMIHS, heterozygous pathogenic variants account for 2% of Thoracic Aortic Aneurysm and Dissection (TAAD), and are also often associated with patent ductus arteriosus." (PMID 35885957, 2022).
thoracic aortic aneurysm (continued). "Familial thoracic aortic aneurysm and dissection (FTAAD), caused by the pathogenic Myh11 K1256del variant, is characterized by impaired aortic contractility; however, how reduced contractility predisposes the aorta to dissection remains incompletely understood." (PMID 41977381, 2026). "Additionally, reports indicate that coding variations and CNVs in MYH11 can contribute to both hereditary and sporadic vascular diseases, including familial and sporadic thoracic aortic aneurysms, as well as other sporadic human vascular diseases." (PMID 40534548, 2025). "Additionally, it has been demonstrated the relationship between MYH11 genetic and epigenetic and thoracic aortic aneurysms and dissections." (PMID 29439675, 2018). "MYH11 is the proposed candidate gene at this interval as defects in this gene underlie aortic aneurysm familial thoracic type 4 (AAT4) [MIM: 132900] and also contribute to familial thoracic aortic aneurysm and dissection (TAAD) and patent arterial duct (PDA)." (PMID 26742958, 2016). "In a third study, mutations in MYH11 [MIM 160745], the gene coding for smooth muscle (SM) myosin heavy chain were shown to trigger patent ductus arteriosus as a congenital trait and the formation of thoracic aortic aneurysms or aortic dissections in adults." (PMID 18159245, 2007). "In addition, dominant mutations in MYH11 are associated with a heritable human vascular disease, thoracic aortic aneurysm and dissection (TAAD), with or without patent ductus arteriosus (PDA)." (PMID 26893369, 2016). "Previously, we developed a familial thoracic aortic aneurysm and aortic dissection (FTAAD) model by deleting K1256 of myosin heavy chain 11 (Myh11), which led to the development of aortic dissection upon stimulation with angiotensin II." (PMID 39596484, 2024).
Patent ductus arteriosus (22 papers, 2007 to 2025). In utero, the ductus arteriosus (DA) serves to divert ventricular output away from the lungs and toward the placenta by connecting the main pulmonary artery to the descending aorta. "MYH11 mutations are associated with Patent Ductus Arteriosus, aortic dissection, and aortic aneurysms." (PMID 39480826, 2024). "MYH11 is involved in smooth muscle contraction and variants in MYH11 are associated with thoracic aneurysm and patent ductus arteriosus." (PMID 39273002, 2024). "Pathogenic variants in MYH11 predispose to a number of disorders, including heritable thoracic aortic disease associated with patent ductus arteriosus, visceral myopathy, and megacystis-microcolon-intestinal hypoperistalsis syndrome." (PMID 39185210, 2024). "Pathogenic variants in MYH11 confer a highly penetrant risk for several disorders, including heritable thoracic aortic disease associated with patent ductus arteriosus." (PMID 39185210, 2024). "FOXF1 was implicated in the disorder through cardiac anomaly related gene ontologies while FOXF1 and MYH11 were implicated through patent ductus arteriosus." (PMID 39480826, 2024). "Pathogenic variants in MYH11 have been described in individuals having TAAD with patent ductus arteriosus (PDA)." (PMID 39125885, 2024). "This notion is compatible with mutations of ACTA2 or MYH11, which display severe vascular consequences including patent ductus arteriosus and familial thoracic aortic dissection." (PMID 34145342, 2021). "A paternally inherited, pathogenic MYH11 variant c.4578+1G>A, resulting in an in-frame loss of 71 amino acids, was identified in a proband with patent ductus arteriosus (PDA)." (PMID 32037394, 2020). "In 2006, two large families with autosomal dominant inheritance of TAAD and patent ductus arteriosus were found to have mutations in the gene encoding myosin heavy chain protein 11 (MYH11) on chromosome 16p137." (PMID 25104961, 2014). "Ascending aortic aneurysms in patients with MYH11 mutations are accompanied by a high rate of patent ductus arteriosus (PDA), but disruption of this locus is responsible for only a small fraction of sporadic PDA." (PMID 28116311, 2017). "Pathogenic variants in MYH11 disrupt this interaction and are associated with familial TAAD, often accompanied by patent ductus arteriosus (PDA)." (PMID 40981152, 2025). "Mutations in myosin heavy chain (MYH11), a smooth muscle cell-specific contractile protein, have been identified in familial TAAD associated with patent ductus arteriosus (PDA) linked to 16p12.2-12.13." (PMID 20937124, 2010). "MYH11 coding variants and MYH11 copy-number variants cause heritable and sporadic vascular disease, including familial TAAD (with or without patent ductus arteriosus), sporadic TAAD, and other sporadic human vascular disorders." (PMID 26893369, 2016). "Various genes, including ACTA2, MYH11, MYLK, and PRKG1, have been identified to be responsible for hereditary non-syndromic TAAD, which is typically accompanied by patent ductus arteriosus (TAAD/PDA)." (PMID 38773466, 2024). "Subsequently, three MYH11 missense mutations have been linked to individuals with TAAD and patent ductus arteriosus (PDA; the ductus arteriosus fails to close postnatally) and rarely to isolated PDA." (PMID 22955375, 2013).
atherosclerosis (19 papers, 2016 to 2025). A disease characterized by the build-up of fatty material and calcium deposition in the arterial wall resulting in partial or complete occlusion of the arterial lumen. "We investigated the association of SMC-specific myosin heavy chain 11 (myosin-11) with atherosclerosis." (PMID 34300321, 2021). "Another recent study documented a high expression of CD68 by MYH11+ SMCs in the intima layer in the early stage of atherosclerosis in humans." (PMID 41301829, 2025). "Immunofluorescence (IF) staining of lesions from two different mouse models of atherosclerosis showed that modulated SMCs, marked by Lumican expression, were concentrated in the fibrous cap, spatially separated from MYH11+ SMCs in the media." (PMID 41107595, 2025). "Given that the proliferation and migration of VSMCs are often accompanied by cell phenotypic transformation during atherosclerosis, we also investigated the protein and mRNA expression levels of contraction phenotypic markers Acta2 and Myh11 in VSMCs." (PMID 37047626, 2023). "We first crossed Myh11-CreERt2/Rosa26-Confetti mice with Apoe−/− mice to assess H3K9me2 levels in atherosclerosis." (PMID 31434493, 2019). "An unannotated disease-specific cell cluster (A-cluster 6) co-expressed contractile VSMC markers (Myh11, Acta2, and Cnn1) with several atherosclerosis-induced ECM genes (Col1a1, Mgp, Eln, Fn1, Col4a1, and Col8a1) and had reduced levels of Ly6a, Vcam1, and Tnfrsf11b compared to imVSMCs." (PMID 40577585, 2025). "Phenotypic modulation of SMCs during human atherosclerosis is characterized by the downregulation of contractile SMC marker genes such as MYH11, TAGLN and CNN1, and activation of gene programs that promote vascular remodeling, lesion development and fibrous cap formation." (PMID 41107595, 2025). "Indeed, in Apoe–/– mice with established Western diet–induced atherosclerosis, Pdgfrb deletion with Myh11-CreERT2 reduces fibrous cap SMA+ cells that are marked by the Myh11-CreERT2 lineage by 50%, without altering the total number of SMA+ cells in the fibrous cap." (PMID 38652543, 2024). "Furthermore, our study indicates that SPP1, CD36, ATP6V0D2, CHI3L1, MYH11, and BDNF, which showed favorable diagnostic performance and high correlations with several clinical biochemical parameters, may potentially serve as biomarkers to diagnose and monitor the prognosis of atherosclerosis." (PMID 31682178, 2019). "We found that VSMCs (Myh11+) undergoing transdifferentiation to macrophages-like cells in human atherosclerotic plaques co-express cleaved caspase 1 as well as IL-1β, indicating the involvement of NLRP3 inflammasome activation in VSMCs phenotypic switch in human atherosclerosis." (PMID 35008765, 2021).
colorectal cancer (18 papers, 2008 to 2026). A primary or metastatic malignant neoplasm that affects the colon or rectum. "Low expression of MYH11 has been reported to be associated with recurrence and metastasis of colorectal cancer." (PMID 33397428, 2021). "In colorectal cancer, survival analysis showed that low expression of MYH11 was significantly associated with poor prognosis." (PMID 35096593, 2021). "A mutation in MYH11 (expressing the smooth-muscle myosin heavy chain) results in human colorectal cancer and intestinal neoplasia formation." (PMID 27121062, 2016). "Supporting this idea, two independent studies identified a high frequency of somatic MYH11 mutations in individuals with a hereditary form of colorectal cancer." (PMID 26893369, 2016). "Recently, heterozygous somatic activating mutations in MYH11, similar to mlt, were reported in human colorectal cancers." (PMID 22973180, 2012). "We identified a somatic frameshift mutation (c.5798delC) in the MYH11 gene in 55% of colorectal cancers (CRCs) with microsatellite instability." (PMID 18796164, 2008). "A total of 155 breast cancer and 71 prostate cancer samples were analyzed for those regions in MYH11 (altogether 8 exons out of 42 coding exons) that harboured mutations in colorectal cancer in our previous study." (PMID 18796164, 2008). "Among these, MYH11+ cancer-associated fibroblasts have been reported to promote tumor migration through interactions with macrophages and were linked to poor prognosis in colorectal cancer." (PMID 41596347, 2026). "Furthermore, it has been found that in stage II and III colorectal cancer, a poor prognosis was linked to downregulated MYH11 expression." (PMID 40918458, 2025). "MYH11 encodes myosin 11, a major contractile protein, that plays important roles in intracellular transport, signal transduction, cell migration and adhesion, and its down-regulation has been linked to poor prognosis in colorectal cancer." (PMID 35576023, 2022). "Mutations in MYH11 have been reported in gastric and colorectal cancers." (PMID 33869179, 2021). "We have previously shown that MYH11 mutations occur in human colorectal cancer, and may also be associated with Peutz-Jeghers syndrome." (PMID 18796164, 2008). "A previous study indicated that MYH11 gene expression is reduced in patients with colorectal cancer or lung cancer, which is correlated with a poor prognosis." (PMID 39762799, 2025). "Moreover, a protein-protein interaction network in a recent work identified MYH11 as a differentially expressed transcription factors in colorectal cancer to be related with metabolism-related genes." (PMID 34380460, 2021). "Furthermore, colorectal cancer patients with lower MYH11 expression inclined to have a dismal prognosis, and poor MYH11 expression evidenced to be an independent adverse prognosticator." (PMID 34380460, 2021). "For instance, lowly expressed MYH11 is connected to the poor prognosis of colorectal cancer." (PMID 32578852, 2020). "MYH11 variants have also been detected in individuals with hereditary non-polyposis colorectal cancer (HNPCC), those with a form of microsatellite instability (MSI) colorectal cancer, and in cases of sporadic cancer with stable microsatellites (MSS cancer)." (PMID 26893369, 2016). "Surprisingly, in the subset of the colorectal cancers examined, the MYH11 mutations were found more frequently in the epithelium, which does not normally express MYH11, than in smooth muscle." (PMID 22973180, 2012). "We have previously identified MYH11 as a driver gene in human colorectal cancer." (PMID 18796164, 2008). "The precise role of the MYH11 mutations in colorectal cancer therefore could not be resolved by these association studies." (PMID 22973180, 2012). "It was reported that MYH11 is not expressed in gastric cancer cell lines and down-regulated MYH11 correlates with poor prognosis in stage II and stage III colorectal cancer." (PMID 30778372, 2018).
colorectal cancer (continued). "It was reported that MYH11, a smooth muscle myosin gene, was down-expressed in MSI colorectal cancer as compared with levels in normal tissues." (PMID 27121062, 2016).
aortic aneurysm (17 papers, 2016 to 2025). A ruptured aneurysm located in the wall of the proximal portion of the descending aorta proceeding from the arch of the aorta. "Adding the causal gene, ACTA2, to list 5+ (n = 19+1) revealed MYH11 with ACTA2 to be associated with Aortic Aneurysm (HP:0004942, q = 2.313x10-3), Aortic Dissection (HP:0002647, q = 5.629x10-3), and Aneurysm (HP:0002647, q = 8.754x10-3)." (PMID 39480826, 2024). "Conversely, the MYH11 gene (rs7205185-G) produces a smooth muscle myosin protein, which has been associated with aortic aneurysm/dissections with a theoretical mechanism of action being hyperplasia leading to an occlusive vascular pathology." (PMID 41542229, 2024). "In particular, the MYH11 represents the most important candidate for the predisposition to Thoracic Aortic Aneurysm and Dissection, while the NDE1 gene represents the strongest candidate for the neurodevelopmental phenotypes." (PMID 30836598, 2019). "Young patients with unusually severe small and large arterial cerebrovascular disease and aortic aneurysms may suffer from MYH11 or other gene pathogenic variants, and a high degree of suspicion by their clinicians will prompt appropriate testing." (PMID 41040781, 2025). "Here we describe a patient, with recurrent ischemic strokes manifested in the fourth and fifth decades of life, multiple intracranial arterial aneurysms and stenotic lesions, and aortic aneurysms, who was found to be a heterozygous carrier of a rare missense variant in the MYH11 gene." (PMID 41040781, 2025). "Many genes have been implicated in the etiology of non-syndromic aortic aneurysm such as ACTA2, MYH11, FLNA, and SMAD3." (PMID 38404628, 2023). "We applied systemic and local lenvatinib treatment to elastase-induced murine aortic aneurysms, and RNA profiling identified myosin heavy chain 11 (Myh11) as the most deregulated transcript." (PMID 34185710, 2021). "Mutations in ACTA2 and MYH11 disrupt proteins involved in SMC contraction and result in predisposition to aortic aneurysms and dissections." (PMID 27586135, 2016). "Aortic aneurysm, left ventricular noncompaction, and early onset Parkinson syndrome have not been reported in association with MYH11 variants." (PMID 37954829, 2023). "In conclusion, this is the first case showing an aortic aneurysm associated with noncompaction and Parkinson syndrome in a carrier of the novel, heterozygous variant c.2225C>T in MYH11." (PMID 37954829, 2023). "For the heterotaxy class, 1/30 (3.3%) cases had a clinically significant result, a 16p13.11 duplication involving the MYH11 gene associated with risk of aortic aneurysm, although this finding does not explain the heterotaxy phenotype." (PMID 34440418, 2021). "For example, MYH11 is involved in the trans-differentiation of fibroblasts in aortic aneurysms." (PMID 32578852, 2020). "In patients with MYH11 variants, the effect of intronic variants on splicing was classified into pathogenic or nonpathogenic variants in aortic aneurysms, so as to ACTA2 variants." (PMID 33083483, 2020). "Myosin heavy chain 11 (Myh11) has been reported associated with aortic aneurysm, but there is no specific study on its function on TAA." (PMID 32578852, 2020). "Meanwhile, MYH11 has been reported to participate in the progression of aortic aneurysm." (PMID 32578852, 2020). "Although it has been demonstrated that mutations affecting the contractile unit, such as ACTA2 and MYH11-gene mutations, contribute to the formation of thoracic aneurysms or dissections, still, little is known about the loss of VSMC contractile function in the pathogenesis of aortic aneurysm." (PMID 34572274, 2021). "Decreases in α-SMA, MYH11, SM22, and CNN1 attenuate HAoSMCs contractility unit formation and further disrupt force generation, promoting the development of aortic aneurysm or dissections." (PMID 34486519, 2021).